PRSS55 (serine protease 55)
Description:
Probable serine protease, which plays a crucial role in the fertility of male mice including sperm migration and sperm-egg interaction.
Synonyms: T-SP1; TSP1; UNQ9391; CT153
Tractability: Antibody: UniProt places it where antibodies can reach, with high confidence; its Gene Ontology location is reachable by antibodies, with high confidence; UniProt predicts a signal peptide or a membrane-spanning region.
Gene: Protein-coding gene on chromosome 8 (10,525,532 to 10,554,166, forward strand). Ensembl gene ENSG00000184647.
Subcellular location: Cell membrane (Isoform 1); Cytoplasm, cytosol; Cytoplasm, cytosol (Isoform 2)
Subcellular location (Human Protein Atlas): Acrosome
Gene Ontology:
Molecular function: serine-type peptidase activity; serine-type endopeptidase activity
Biological process: binding of sperm to zona pellucida; flagellated sperm motility; protein processing; proteolysis
Cellular component: plasma membrane; acrosomal vesicle; cytosol
Genetic constraint (gnomAD): Loss-of-function variants: 42 observed, 24.01 expected, observed/expected ratio (o/e) 1.75, 90% interval 1.34 to 1.96. The synonymous counts are far from expectation, so gnomAD's model fits this gene poorly and the ratio says little. Missense variants: 651 observed, 447.07 expected, observed/expected ratio (o/e) 1.46, 90% interval 1.37 to 1.55. Synonymous variants: 240 observed, 171.7 expected, observed/expected ratio (o/e) 1.4, 90% interval 1.26 to 1.56.
Homologues: Orthologues: chimpanzee PRSS55 (97% identical), macaque PRSS55 (70% identical), dog PRSS55 (67% identical), rabbit PRSS55 (55% identical), rat Prss55 (54% identical), mouse Prss55 (54% identical), guinea pig PRSS55 (52% identical), zebrafish f9a (26% identical), tropical clawed frog cfi (24% identical), zebrafish habp2 (24% identical), Drosophila melanogaster CG31266 (20% identical), Drosophila melanogaster CG31267 (18% identical). Paralogues in human: F11 (30% identical), KLKB1 (30% identical), PRSS51 (27% identical), HGFAC (25% identical), F12 (25% identical), F10 (24% identical), F7 (24% identical), C1R (24% identical), C1S (24% identical), CFI (24% identical), F9 (24% identical), CFD (22% identical), and 4 more.
Diseases named in the same sentence as PRSS55 in open-access papers:
PRSS55 is named in the same sentence as 11 diseases in open-access papers, as found by Europe PMC text mining. Sharing a sentence is not in itself a finding about the gene and the disease. The quoted sentences say what the papers report.
male infertility (4 papers, 2018 to 2025). The inability of the male to effect fertilization of an ovum after a specified period of unprotected intercourse. "Genetic ablation of either Tmprss12 or Prss55 in mice results in male infertility, primarily due to the inability of sperm to successfully navigate the uterotubal junction (UTJ) and reach the site of fertilization." (PMID 40764777, 2025). "To further confirm the phenotype of male infertility of Prss55-KO mice, we performed the analysis of in vivo fertilization rate." (PMID 30032357, 2018). "Together, these data indicate that Prss55 deficiency in mice leads to male infertility but not female infertility, consistent with the testis-specific expression pattern of PRSS55." (PMID 30032357, 2018). "As a serine protease, PRSS55 might function by activating these II muscle myosins in the testis, which then participate in sperm structural differentiation and further affect its function, a defect in which could lead to male infertility." (PMID 33417308, 2021). "We generated single KO mice lacking Prss55 and found that the Prss55 KO mice exhibited severe male infertility and sperm–ZP binding in vitro." (PMID 32301961, 2020). "A recent study has shown that mice lacking Prss55 exhibit severe male infertility; Prss55 KO spermatozoa fail both to migrate from the uterus into oviduct in vivo and to bind ZP of oocytes in vitro." (PMID 32301961, 2020).
Infertility (2 papers, 2018 to 2025). "While the precise molecular mechanisms are still under investigation, the infertility phenotypes associated with Tmprss12 and Prss55 knockouts highlight their potential as targets for male contraception." (PMID 40764777, 2025). "This research successfully establishes that a humanized PRSS55 transgene, particularly the RES TM construct, can effectively rescue the infertility phenotype in Prss55 knockout mice." (PMID 40764777, 2025). "This study aimed to evaluate the potential of human PRSS55 and human TMPRSS12 to rescue the infertility phenotypes observed in their respective mouse knockout models, thereby establishing humanized mouse models for future contraceptive drug testing." (PMID 40764777, 2025). "Therefore, this study aimed to investigate the efficacy of human PRSS55 and human TMPRSS12 in rescuing the infertility phenotypes of their respective knockout mouse lines." (PMID 40764777, 2025). "Both humanized PRSS55 transgenic lines, RES GPI (extracellular tag) and RES TM (intracellular tag), were capable of siring offspring in the Prss55d/d background, which is otherwise infertile." (PMID 40764777, 2025). "This study investigated whether human orthologs of two mouse testis-specific serine proteases, PRSS55 and TMPRSS12, both essential for male fertility in mice, could functionally rescue the infertility phenotypes of their respective knockout mouse lines." (PMID 40764777, 2025). "The in vivo fertilization rate calculated as the percentage of the 2-cell embryos was 82.9% in wt mice and 4.1% in mutant mice, suggesting that the infertility of Prss55−/− males was mainly due to the fertilization defects but not due to the developmental disability of the embryos." (PMID 30032357, 2018).
Obesity (2 papers, 2020 to 2021). Accumulation of substantial excess body fat. "From the GWAS, the significant markers associated with obesity-related traits including body weight (CACNA1B, C22orf39, U6, MYH14, PTPN2, SEH1L) and blood sugar (PRSS55, GRIK2), were identified." (PMID 33182249, 2020).
ovarian carcinoma (1 paper, 2019). A malignant neoplasm originating from the surface ovarian epithelium. "Another protein is the Protease Serine 55 (PRSS55) along with the variant rs4404875, which has been mainly identified in Leydig and Sertoli cells and it is is associated with prostate and ovarian cancer." (PMID 31354629, 2019).
teratozoospermia (1 paper, 2021). "PRSS55 is likely to be a potential pathogenic factor in male astheno/teratozoospermia." (PMID 33417308, 2021). "These could be the potential causes of the astheno/teratozoospermia phenotype of the Prss55−/− mice, and provided new evidence for the previously reported impaired sperm‐UTJ migration." (PMID 33417308, 2021). "Thus, PRSS55 is essential for the structural differentiation and energy metabolism of sperm, and might be a potential pathogenic factor in astheno/teratozoospermia." (PMID 33417308, 2021).
cardiovascular disease (1 paper, 2023). "As for Prss55, DrugBank analysis showed that there are no potential targeted drugs directly related to cardiovascular disease treatment." (PMID 38089628, 2023).
PRSS55 also shares sentences with these, for which no sentence is quoted: cancer (2 papers); female infertility (1); Insulin resistance (1); type 1 diabetes mellitus (1); type 2 diabetes mellitus (1).